NLRP3 (NLR family pyrin domain containing 3)
Diseases named in the same sentence as NLRP3 in open-access papers (continued):
Sharing a sentence is not in itself a finding about the gene and the disease.
ischemic stroke (continued). "In a word, EA could decrease the inflammation, infarct volume, and neurological dysfunction through suppressing the expression level of NLRP3 inflammasome mediated by 7nAChR and miR-223 in ischemic stroke." (PMID 32581721, 2020). "Besides, due to the complexity of the pathogenesis of ischemic stroke, it is important to determine the stages of disease at which the NLRP3 inflammasome targeted treatment is effective." (PMID 32581721, 2020). "This shows that the TXNIP/NLRP3 inflammasome is an important contributor to ischemic stroke." (PMID 31174550, 2019). "The NLRP3 inflammasome components activation have great promotion effects on microglia/macrophage polarization, thereby exacerbating the inflammatory response in the acute phase of ischemic stroke." (PMID 31920554, 2019). "However, there are many patients that are afflicted by both T2DM and ischemic stroke, and the possible effects of NLRP3 regulation for these patients are not well understood." (PMID 31174550, 2019). "Most importantly, increasing evidence in mouse models indicates that inhibition of the NLRP3 inflammasome may protect against neurological deterioration after ischemic stroke and decrease the infarct volume." (PMID 31174550, 2019). "Previous studies have provided much evidence that downregulation of NLRP3 may help treat both diabetic patients and ischemic stroke patients." (PMID 31174550, 2019). "Notably, NLRP3 is associated with inflammatory responses which play a crucial role in SBI after ICH and ischemic stroke." (PMID 29970985, 2018). "NLRP3 inflammasome signal pathway is considered as a novel therapeutic target for ischemic stroke." (PMID 30647760, 2018). "MCC950, the NLRP3 specific inhibitor, ameliorated diabetic mice with cerebral ischemia-reperfusion injury and improved the 28-day survival rate during the recovery stage of ischemic stroke." (PMID 29853850, 2018). "It is further suggested that the possible prognosis of ischemic stroke in diabetic mice may be due to the involvement of NLRP3 inflammasome." (PMID 29853850, 2018). "Moreover, KD pre-treatment suppressed NLRP3 inflammasome activation by inhibiting Drp1-mediated mitochondrial fission and ER stress, which alleviated brain dysfunction in ischemic stroke." (PMID 29662437, 2018). "Furthermore, intravenous immunoglobulin has been shown to suppress NLRP3 inflammasome-mediated neuronal cell death after ischemic stroke and to improve neurological outcome." (PMID 27843532, 2016). "Our study indicates that BTK is essential for NLRP3 inflammasome activation and could be a potent therapeutic target in ischaemic stroke." (PMID 26059659, 2015). "Moreover, KG treatment deactivates NLRP3 inflammasomes, which could be used as a novel therapeutic target for the clinical management of ischemic stroke." (PMID 40272769, 2025). "However, whether UA has efficacy in suppressing NLRP3 inflammasome-mediated microglia pyroptosis in ischemic stroke is still unclear." (PMID 40717974, 2025). "Moreover, NLRP3 inflammasome activation can up-regulate the IL‐1β expression and further promote the cascade of inflammation in the central nervous system, leading to the aggravation of nerve injury in patients with ischemic stroke." (PMID 41246459, 2025). "To confirm the role of NLRP3 in ischemic stroke in our findings, we examined whether the beneficial effect of KG diet was mediated via NLRP3 inflammasome using genetic knocking down of NLRP3 after ischemic stroke." (PMID 40272769, 2025). "Therefore, the Sirt1/NLRP3 signaling pathway may attenuate the development of neuroinflammation in ischemic stroke." (PMID 40160465, 2025). "Moreover, mitophagy may mitigate brain damage in ischemic stroke rats via its inhibitory effect on NLRP3 inflammasome activation." (PMID 40260133, 2025). "Moreover, the NLRP3 inflammasome has been reported to mediate inflammatory reactions during ischemic stroke and ROS may be required for NLRP3 inflammasome activation." (PMID 37728582, 2024).
ischemic stroke (continued). "However, while the NLRP3 inflammasome is elevated in the post-stroke brain, it has been reported that it has minimal contribution to brain injury and neurological function after experimental ischemic stroke." (PMID 39742155, 2024). "However, it is debated whether NLRP3 inhibition can reduce infarct volume in experimental ischemic stroke." (PMID 38216560, 2024). "Therefore, we sought to explore whether ChemR23 signaling works through NLRP3 inflammasome pathway in ischemic stroke." (PMID 38178174, 2024). "Thus, targeting NLRP3 inflammasome-mediated neuronal pyroptosis may provide new insight and a theoretical basis for developing an effective treatment for ischemic stroke." (PMID 38178174, 2024). "In addition, the NLRP3 protein is upregulated following ischemic stroke." (PMID 37353794, 2023). "However, the precise alteration in BRCC3 levels and whether TENS exerts counteracting effects on oxidative stress and inflammasomes by TXNIP and BRCC3/NLRP3 signaling have barely been investigated in ischemic stroke." (PMID 37101593, 2023). "Therefore, through our bibliometrics we found that in the last 2 years, acupuncture treatment has been carried out in the field of ischemic stroke and that acupuncture treatment may protect against ischemic stroke injury by decreasing NLRP3 expression." (PMID 37088947, 2023). "However, the effect of NBP on the NLRP3 inflammasome during and after ischemic stroke remains unknown." (PMID 36013423, 2022). "Therefore, further understanding of the role of NLRP3 inflammasome may open a new window for potential approaches to ischemic stroke therapy and brain repair/rehabilitation." (PMID 35328506, 2022). "PN via activating NLRP3 inflammasome could contribute to HT and poor outcomes in ischemic stroke." (PMID 36238294, 2022). "Vinp via inhibiting NLRP3 inflammasome expression could attenuate ischemic stroke in mice." (PMID 36238294, 2022). "In addition, after exercise preconditioning, the expression of NLRP3 inflammasome was reduced, the composition and the beta diversity of gut microbiota were remodeled, and the impairment of cognitive function was alleviated in ischemic stroke." (PMID 36262547, 2022). "Another study also found that Tranilast, an NLRP3 inflammasome inhibitor, could promote the polarization of microglia/macrophage from M1 type to M2 type and ameliorate ischemic stroke by inhibiting the NLRP3/caspase-1 pathway in a murine model of distal middle cerebral artery occlusion." (PMID 36035210, 2022). "Our data shows that ISO pretreatment can downregulate NLRP3, caspase-1, and IL-1β mRNA and protein levels in the retina after ischemic stroke, suggesting that the protective mechanisms underlying ISO pretreatment may be related to the direct inhibition of retinal NLRP3 inflammasome activation." (PMID 34305534, 2021). "Furthermore, emerging evidence suggested that the elevated expression of NLRP1 and NLRP3 inflammasome proteins could be modulated by the NF-κB signaling pathway in ischemic stroke." (PMID 34646128, 2021). "IMM-H004, a novel coumarin derivative, could decrease the expression level of chemokine-like factor 1 (CKLF1) combining with C-C chemokine receptor 4, further inhibiting the NLRP3 inflammasome activation and inflammation, thereby exerting therapeutic effects on rats following ischemic stroke." (PMID 32581721, 2020). "Therefore, the modulation of NLRP3 inflammasome activation at the molecular level may give us an insight into the development of new therapeutics for ischemic stroke." (PMID 32625078, 2020). "Besides, ruscogenin is a crucial steroid sapogenin derived from Ophiopogn japonicus, and ruscogenin could improve neurological dysfunctions of ischemic stroke mice via suppressing expression levels of NLRP3, IL-1β, caspase-1, TXNIP, MAPK, and ROS." (PMID 32581721, 2020).
ischemic stroke (continued). "The NLRP3 inflammasome may mediate neuronal and glial cell death in ischemic stroke through a number of mechanisms, by increasing the production and secretion of the pro-inflammatory cytokines IL-1β and IL-18 and through the pleiotropic effects of cleaved caspase 1 in mediating brain cell apoptosis." (PMID 31174550, 2019). "However, the specific cellular location and signaling pathway of NLRP3 inflammasomes in ischemic stroke remains unknown." (PMID 30153825, 2018). "Our study indicates that the NLRP3 gene polymorphism rs4612666 may be associated with the occurrence of LAA ischemic strokes and MES in the Chinese Han population, suggesting that the NLRP3 gene polymorphism influences the susceptibility of LAA IS by changing plaque vulnerability." (PMID 29850543, 2018). "Recently, a novel inflammatory pathway, known as inflammasomes, was found in ischemic stroke, and several studies have highlighted that nod-like receptor protein 3 (NLRP3) inflammasomes may be crucial for mediating inflammatory responses and for inducing cellular damage and death after stroke." (PMID 30153825, 2018). "However, the mechanism by which Drp1 regulates NLRP3-mediated inflammation in ischemic stroke remains unclear." (PMID 29662437, 2018). "In addition, we summarize the recent researches on the role of NLRP3 inflammasome in central nervous system (CNS) diseases, including traumatic brain injury, ischemic stroke and hemorrhagic stroke, brain tumor, neurodegenerative diseases, and other CNS diseases." (PMID 27652274, 2016). "Thus, inhibiting ROS generation and modulating the TXNIP/NLRP3 pathway might be beneficial for prevention and treatment of ischemic stroke." (PMID 27589720, 2016). "For example, in a mouse model of ischemic stroke, microglia‐specific PGC‐1α overexpression suppresses NLRP3 inflammasome activation; reduces TNF‐α, IL‐1β, and IL‐6 production; enhances mitophagy; and significantly improves neurological outcomes." (PMID 41517974, 2026). "The lncRNA NEAT1 regulates NLRP3 inflammasome activation in microglia by forming a NEAT1/miR-10b-5p/BCL6/NLRP3 axis, thereby mitigating the harmful outcomes of ischemic stroke-induced inflammation." (PMID 39847586, 2025). "Previous reports have shown the contribution of inflammation in the pathogenesis of ischemic stroke, whereas NOD-like receptor family pyrin domain-containing 3 (NLRP3) inflammasome plays a crucial role." (PMID 40272769, 2025). "For instance, the mediating effect of peroxynitrite anions can activate MMPs and NLRP3 inflammasomes, exacerbating BBB damage and hemorrhagic transformation, and leading to a poorer prognosis in hyperglycemic ischemic stroke patients." (PMID 39865270, 2025). "It has been shown that inhibition of NLRP3 inflammasome activation significantly reduces BBB damage, ischemic stroke infarct size, and endothelial cell death through pyroptosis regulation." (PMID 39753298, 2025). "The NF-κB/NLRP3/GSDMD pathway is a significant anti-pyroptotic and neuroprotective pathway after ischemic stroke." (PMID 40717974, 2025). "In treating ischemic stroke, RNA binding protein RPS3 regulates microglial pyroptosis and neuronal damage through the Sirt1/NLRP3 pathway." (PMID 40160465, 2025). "Cerebral ischemia-reperfusion damage was alleviated to different degrees, suggesting that the NF-κB/NLRP3/Caspase-1/GSDMD signaling pathway is involved in the pathogenesis and healing of ischemic stroke." (PMID 39199474, 2024). "For example, NLRP3, CASP 1, and IL-1β were found to colocalize in cortical neurons in ischemic stroke animal models." (PMID 38920626, 2024). "Thus, ChemR23 signaling may regulate NLRP3 inflammasome pathway in ischemic stroke." (PMID 38178174, 2024). "The NLRP3 inflammasome mediates inflammation in traumatic brain injury (TBI), ischemic stroke, and ICH, and NLRP3 inhibition reduces inflammation and improves outcomes in all these models of neurological injury." (PMID 39636949, 2024).
ischemic stroke (continued). "In ischemic stroke models, bile acid-induced TGR5 activation reduces the expression of NLRP3 inflammasomes and IL-1β, offering therapeutic benefits." (PMID 39328272, 2024). "Following ischemic stroke (IS), the NLRP3 or NLRP1 protein forms a multi-protein complex known as the NLRP3 or NLRP1 inflammasome by binding with Caspase-1 precursor and ASC." (PMID 38601463, 2024). "Enhanced HIF-1α levels after ischemic stroke appear to be involved in RIPK3/MLKL activation, leading to activation of the NLRP3 inflammasome." (PMID 38674050, 2024). "In conclusion, our results indicated that TENS alleviated brain damage following ischemic stroke via inhibiting neuronal oxidative stress and pyroptosis and activating mitophagy, possibly via the regulation of TXNIP, BRCC3/NLRP3, and HIF-1α/BNIP3 pathways." (PMID 37101593, 2023). "However, factors triggering NLRP3 inflammasome activation in ischemic stroke remain unknown." (PMID 37353794, 2023). "In ischemic stroke, the TLR4/NF-κB pathway has the ability to trigger the activation of NLRP3 inflammasome, which in turn regulates pyroptosis." (PMID 38273974, 2023). "In contrast, TREM1 mediates neuroinflammation in ischemic stroke by interacting with the SYK signaling pathway to activate downstream NF‐κB and NLRP3 inflammasome." (PMID 38680509, 2023). "In contrast, TREM1 mediates neuroinflammation during an ischemic stroke by interacting with the spleen tyrosine kinase (SYK) signaling pathway and activating downstream nuclear factor kappaB (NF‐κB) and NLRP3 inflammasome." (PMID 38680509, 2023). "Therefore, the NLRP3 inflammasome may be a promising therapeutic approach for ischemic stroke." (PMID 37915409, 2023). "We also discuss the role of medicinal interventions that target the NLRP3 and potential pathways, as well as possible directions for curcumin therapy to penetrate the blood–brain barrier (BBB) and hinder inflammation in ischemic stroke." (PMID 37915409, 2023). "In the present study, we conducted an IPC model in vivo and in vitro to explore the relationship between the NLRP3 inflammasome and IPC after ischemic stroke." (PMID 37371374, 2023). "The mRNA expression levels of NLRP3, SIRT1, and IL-18 on an animal model of ischemic stroke with CPSP were measured by qRT-PCR to validate the data mining findings from GEO." (PMID 36059399, 2022). "In addition, although there is evidence that nuclear factor (NF)‐kB and mitogen‐activated protein kinase (MAPK) signalling promotes neuronal NLRP inflammasome activation following ischaemic stroke, the precise mechanisms that contribute to post‐stroke NLRP3 inflammasomes activation remain unknown." (PMID 34866334, 2022). "The difference in NLRP3 and NLRC4 expression under ischemic stroke conditions remains to be elucidated." (PMID 35937897, 2022). "Our study first proved that NLRP3 KO has a protective effect against CIRI after MCAO and then proved that KO also effectively alleviates lung injury induced by ischemic stroke and prevents SAP." (PMID 35432726, 2022). "Finally, following an ischemic stroke—hypoxia, vascular obstruction, and cerebral parenchyma injury/ischemia lead to anaerobic glycolysis—this leads to the excessive accumulation of hydrogen ions (H+) and lactic acid, which induces acidosis and subsequent NLRP3 activation." (PMID 35328506, 2022). "After injury resulting from ischemic stroke, elevated extracellular ATP concentrations activate P2X7, triggering a series of intracellular responses that lead to NLRP3 inflammatory body activation and assembly." (PMID 34276530, 2021). "NLRP3 inflammasome, as the most featured member of the NLR family, participates in neuronal apoptosis after ischemic stroke." (PMID 34257822, 2021). "SYK inhibitor R406 significantly deactivated NLRP3, Caspase-1, and GSDMD-N signaling; reduced the concentration of IL-1β; and attenuated GSDMD-N induced membrane pores in mice with ischemic stroke." (PMID 33402173, 2021).
ischemic stroke (continued). "NLRP3, a member of NOD-like receptor signaling pathway, plays a vital role in the progression of ischemic stroke, suggesting NLRP3 as a potential treatment target for ischemic stroke." (PMID 34707562, 2021). "After ischemic stroke, TXNIP exacerbates cerebral injury through redox imbalance and subsequently activates the NLRP3 inflammasome." (PMID 34059091, 2021). "We found that the serum concentration of NLRP3 was positively correlated to CASP1, providing preliminary clinical evidence to the involvement of pyroptosis in ischemic stroke." (PMID 34493232, 2021). "Accordingly, ischemic stroke was found to significantly increase the levels of cleaved caspase-1, ASC, NLRP3, cleaved GSDMD, IL-1β, and IL-18." (PMID 33584203, 2020). "In ischemic stroke, MAPK and NF-κB signaling pathways are key links in the expression and activation of NLRP1 and NLRP3 inflammatory corpuscles." (PMID 33424599, 2020). "Besides, light-emitting diode (LED) treatment could decrease neuroinflammatory reactions and brain damage after ischemic stroke via reducing cell death, decreasing IL-1β and IL-18, and inhibiting NLRP3 inflammasome, MAPK signaling, TLR-2 levels and NF-κB activation." (PMID 32581721, 2020). "For example, ischemic stroke was shown to activate both NLRP1 and NLRP3 inflammasomes in neurons through nuclear factor kappa-light-chain-enhancer of activated B cells (NF-κB)- and mitogen-activated protein kinase-dependent mechanisms." (PMID 33328988, 2020). "Also, ketogenic diets may inhibit ER stress and protect mitochondrial integrity from ischemic brain damage via inhibiting mitochondrial transposition of dynamin-related protein 1 (Drp1), thereby suppressing activation of NLRP3 inflammasome and playing a neuroprotective role in ischemic stroke." (PMID 32581721, 2020). "Previous preclinical work in ischaemic stroke has found that the BTK inhibitor ibrutinib inhibits IL-1β maturation and NLRP3 inflammasome activation in infiltrating macrophages and neutrophils in the infarct area of the MCAO model." (PMID 30758770, 2019). "Inflammation plays an important role in the pathogenesis of ischemic stroke, and the role of nucleotide-binding domain (NOD)-like receptor protein 3 (NLRP3) inflammasome in stroke has been a focus in current studies." (PMID 29662437, 2018). "Here, the authors show that Bruton's tyrosine kinase is essential for NLRP3 inflammasome activation, and that blocking it with the FDA-approved inhibitor ibrutinib limits tissue damage in a mouse model of ischaemic stroke." (PMID 26059659, 2015). "The absence of NLRP3 can ameliorate brain injury in mice after ischemic stroke by reducing infarction and blood‒brain barrier (BBB) damage." (PMID 40075143, 2025). "For example, after ischemic stroke, OGD (oxygen–glucose deprivation) induces upregulation of lncRNA H19, which competes for binding with miR‐423‐5p to regulate NOD‐like receptor protein 3 (NLRP3), promoting inflammatory response and inhibiting neurogenesis." (PMID 40346986, 2025). "This miRNA regulates the NLRP3 inflammasome by targeting TRAF6 and may become a novel therapeutic target for ischemic stroke." (PMID 38361743, 2024). "Furthermore, edaravone dexborneol exerted neuroprotective effect by inhibiting NF-κB/NLRP3/GSDMD signaling pathway and inflammatory factors (IL-1β and IL-18) in experimental ischemic stroke." (PMID 38902691, 2024). "In the current study, we aim to investigate whether NLRP3 inflammasome and cell pyroptosis are involved in the neuroprotective mechanism of IPC after ischemic stroke." (PMID 37371374, 2023). "The endogenous protective effects and the relationship between IPC and the NLRP3 inflammasome after ischemic stroke have not been elucidated." (PMID 37371374, 2023).